FAP (fibroblast activation protein alpha)
Diseases named in the same sentence as FAP in open-access papers (continued):
Sharing a sentence is not in itself a finding about the gene and the disease.
tumor (continued). "FAP is a membrane protease in cancer-associated stromal fibroblasts and contributes to tumor progression but is absent or insignificant in most normal tissues." (PMID 37864148, 2023). "High and low expression of FAP was confirmed in representative fixed tumor tissues on IHC staining." (PMID 38706713, 2023). "In this study, we discovered that FAP(+) CAFs at the EOCC tumor invasive margin showed an upregulation of the WNT signaling and may affect neighbor PanCK(+) tumor epithelial cells via the FGF20-FGFR2-PI3K/AKT signaling pathway." (PMID 37964075, 2023). "Indeed, FAP is mostly secreted by adipose stromal CAFs in tumor microenvironment, which are predominant in the Luminal A molecular subtype (while the fibrous stroma is prevalent in HER-2, Luminal B and triple-negative subtypes)." (PMID 36765866, 2023). "Results of the qualitative and semiquantitative visual assessment of FAP tumor staining." (PMID 37727209, 2023). "The high expression of FAP in tumor interstitium and the poor prognosis of tumor patients suggests that FAP is a key factor in tumor growth, proliferation, invasion and metastasis, which further makes FAP the most prominent target for tumor diagnosis and treatment in the field of nuclear medicine." (PMID 36986521, 2023). "In addition, the reduction of FAPα-expressing CAFs significantly attenuates the expression of collagen I and various stromal factors that contribute to tumor progression." (PMID 37254126, 2023). "Fibrogenesis in S‐ECM samples is likely due to the presence of an activated cancer‐associated fibroblast (CAF) population in the tumor microenvironment, as indicated by the identification of CAF marker genes as key regulators for S‐ECM, including FAP, ACTA2, PDGFRB, VCAN, and ITGA11." (PMID 36637997, 2023). "In addition, overexpression of the TCF21 in CAFs with high FAP, which is exclusive to low levels of FAP, can impair the ability of CAFs to promote tumor invasion, chemoresistance, and progression." (PMID 37723510, 2023). "Interestingly, we discovered that FAP-targeted CAR-T cells inhibit MDSCs in tumor sites and further promote the infiltration and survival of sequentially CLDN18.2-targeted CAR-T cells." (PMID 37046312, 2023). "Furthermore, we also evaluated the expression of myofibroblast marker genes, such as COL1A2, COL3A1, ACTA2, and FAP, in the tumor microenvironment using an IHC assay." (PMID 37953225, 2023). "A plausible reason for this observation may be that FAP functions through different mechanisms in different tumor cells." (PMID 36382346, 2023). "Fibroblast activation protein alpha (FAP), which is also a cancer signature gene, is involved in extracellular matrix degradation and many cellular processes, including tissue remodeling, fibrosis, wound healing, inflammation, and tumor growth." (PMID 38063927, 2023). "The significance of our results shows that FAP is crucial in tumor progression." (PMID 37892020, 2023). "[177Lu]21 demonstrated a similar distribution by SPECT as [18F]21 with a significant and specific tumor uptake that could be visualized up to 6 days, indicating a prolonged retention in FAP-positive tumors." (PMID 36864362, 2023). "However, clinical trial results so far, while affirming a good safety profile for FAP-targeting, have exhibited very limited anti-tumor efficacy." (PMID 37251405, 2023). "For the essential interstitial components throughout the whole process of tumor genesis and proliferation, FAP-related indicators are potentially more stable and reliable in developing a molecular imaging protocol than microenvironment-based ones, such as immunoPET." (PMID 36986521, 2023). "Furthermore, analyses of tumor-surrounding fibroblasts showed a significant positive correlation between high FAP expression and the occurrence of lymph node metastases, disease recurrence, and death in patients with PDAC." (PMID 37046710, 2023).
tumor (continued). "Depletion of these markers may be beneficial, as FAPα-expressing vaccines reduce tumor growth by generating a FAPα-specific CTL response capable of killing CAFs." (PMID 37254126, 2023). "Additionally, we demonstrate the effectiveness of pre-treating stromal solid tumors with FAP(hF1) UCAR T cells before administering tumor-antigen targeting CAR T-cells, in this instance Meso UCAR T-cells." (PMID 37251405, 2023). "It has been proven that FAP inhibition leads to a decrease in tumor vascularization." (PMID 36835275, 2023). "FAP is a serine peptidase that share 70% of the sequence identity with the enzyme dipeptidyl-peptidase to facilitate extracellular matrix reorganization and promote tumor malignancies." (PMID 37325617, 2023). "In breast tumors with a high stromal content, radiolabeled FAP-specific enzyme inhibitor (FAPIs) may offer high contrast for fast imaging and could serve as anti-tumor agents." (PMID 37496657, 2023). "[68Ga]Ga-FAP-2286-ICG PET/CT displayed significantly high uptake in all three tumor types of HNC." (PMID 38026901, 2023). "FAP has been identified as a candidate universal target antigen due to its reported selective expression in nearly all solid tumors by a subset of immunosuppressive tumor stromal fibroblasts." (PMID 38516299, 2023). "Dramatically increased numbers of tdTomato+ Meso-CAR T cells started to infiltrate into both tumor stroma and tumor nest regions, even at day 1 post-second treatment in tumors first treated with FAP-CAR T cells compared with the tumors first treated with MigR control or Meso-CAR T cells." (PMID 37607999, 2023). "However, the FAPI tetramer applied in our study was designed to improve tumor uptake and retention so as to enhance the antitumor efficacy of FAP-targeted radioligand therapy." (PMID 37321827, 2023). "Further, FAP was positively correlated with endothelia cells infiltration, suggesting that FAP may participate in tumor progression by promoting angiogenesis." (PMID 37166418, 2023). "Moreover, in vivo depletion of fibroblast activation protein (FAP)+ stromal cells, a marker abundantly expressed by CAFs, resulted in the inhibition of tumour growth." (PMID 37240052, 2023). "IHC analysis confirmed higher levels of CD8+ T cell tumor infiltrates with the combination 177Lu-FAP-2287 plus anti-PD1 on day 8 pi, with the number of CD8+ T cells increasing to 10.6% of total cells versus to 4.9% (P = 0.0018) and 6.0% (P = 0.0190) in vehicle and anti-PD-1 groups, respectively." (PMID 37086273, 2023). "Spatial transcriptomic analysis of 112 areas of interest, using NanoString GeoMx digital spatial profiling, demonstrate that FAP(+) CAFs at the EOCC tumor invasive margin show a significant upregulation of WNT signaling and higher mRNA/protein levels of fibroblast growth factor 20 (FGF20)." (PMID 37964075, 2023). "Further modifications are needed to improve the binding affinities, pharmacokinetics, and tumor uptake of 68Ga-labeled PSMA/FAP bispecific tracers by considering the linker’s length, lipophilicity, and the use of less lipophilic PSMA- and/or FAP-targeting pharmacophores." (PMID 36770755, 2023). "Indeed, FAP activates inflammatory CAFs by triggering STAT3, which is an important transcription factor involved in tumor-associated inflammation." (PMID 38313431, 2023). "HT1080-FAP tumors have stable FAP expression on tumor cells through lentivirus transfection." (PMID 38706713, 2023). "Another vaccine reduced the growth of 4T1 tumors by promoting production of cytotoxic T lymphocytes that killed CAFs, and the decrease in FAPα-expressing CAFs markedly decreased collagen I and other stromal factors, resulting in a marked attenuation of tumor progression." (PMID 37496657, 2023). "FAPI-PET may also prove useful in biopsy planning given the heterogeneous uptake in the tumor and the importance of FAP for invasive growth, in turn suggestive of the presence of active tumor cells in areas with high tracer uptake." (PMID 39355017, 2023).
tumor (continued). "Remarkably, combination treatment of Meso UCAR T-cells with both FAP(hF1) and FAP(mF3) UCAR T-cells not only restored but further enhanced anti-tumor activity against the HCC70+CAF spheroids significantly, relative to Meso UCAR T-cell activity against HCC70 spheroid alone." (PMID 37251405, 2023). "In conclusion, our study demonstrate how spatial cell-states like FAP(+) CAFs may have clinical implications at the tumor invasive margin of EOCC tumors by affecting neighbor tumor epithelial cells." (PMID 37964075, 2023). "The goal of targeting FAP is to disrupt the tumor microenvironment and inhibit cancer cell growth." (PMID 37583569, 2023). "Notably, we observed a significant decrease in the number of MDSCs in tumor tissue of the FAP-targeted CAR-T treatment group compared with the CLDN18.2-targeted CAR-T and UTD groups." (PMID 37046312, 2023). "We stained several fixed tumor samples from our laboratory using an anti-FAP antibody." (PMID 38706713, 2023). "Herein, we investigated the relationship between FAP expression and infiltration of tumor microenvironment stromal cells, with the aim to decipher the role of FAP in tumor immunology and better understand the effect of these immune components with tumor development." (PMID 37166418, 2023). "In addition, compared to [177Lu]Lu-FAPI-46, [177Lu]Lu-FAP-2286 showed longer tumor retention (up to 72 h) and better tumor control." (PMID 36813980, 2023). "In addition, FAP has been shown to act as an activator of CD40 in tumor models of mice, enhancing dendritic cell activation and initiating T cell action." (PMID 37006278, 2023). "With regard to the contributing role of CAFs in the formation of tumor microenvironment, we investigated whether rAd‐FAP/hlivin α‐transduced DCs could enhance the cytotoxic effect of splenic lymphocytes on CAFs in vitro." (PMID 37773704, 2023). "The disassembly of these nanoparticles upon FAP-α cleavage led to the efficient release of the encapsulated drugs at tumour sites, and superior therapeutic efficacy for a variety of solid experimental tumours including xenograft MCF-7 breast tumour models." (PMID 37048731, 2023). "Importantly, FAP overexpression promotes the infiltration of NK92 cells into human tumor xenografts, suggesting a role for manipulating FAP expression to promote NK cell therapeutics." (PMID 38196606, 2023). "Moreover, as CAFs reportedly can compete metabolically with T cells, FAP-CAR T cells also likely alter the metabolic status of the TME in favor of endogenous anti-tumor immunity and functionality of adaptively transferred CAR T cells." (PMID 37607999, 2023). "As such, the broad depletion of stromal cells by FAP-CAR T cells may induce the reduction of tumor-enhancing growth factors including HGF and c-Met, thus limiting the proliferation and invasiveness of cancer cells." (PMID 37607999, 2023). "Furthermore, the tumor-promoting effect of FAP-positive CAFs is partly mediated by attracting more MDSCs or macrophages to tumor sites, where they enhance the stemness of cancer cells and/or promote the expansion of cancer stem cells." (PMID 38017374, 2023). "Further, FAP-based WCTV could have significant anti-tumor properties, slowing tumor growth and reducing the recurrence rate by eliciting host immune response in which antigen-specific cytotoxic T cells and CD4+ T lymphocytes participate." (PMID 37316886, 2023). "In these studies, we added AF647-anti-CD31 to the slices to image vasculature in addition to PE-CD90.2 to image stromal cells in slices from mCerulean+ 4662 tumor-bearing mice at baseline (prior to FAP-CAR T cell administration) and 6, 12, and 18 hours post FAP-CAR T cell administration." (PMID 37607999, 2023). "Also important was the observation that a first dose of FAP-CAR T cells enhanced the activation of CD45.2+tdTomato+ Meso-CAR T cells in tumor sites, as demonstrated by increased expression of GzmB, TNF-α, and IFN-γ after stimulation." (PMID 37607999, 2023).
tumor (continued). "Similarly, the Nb-TriTE also redirected the cytotoxicity of T cells toward other human FAP-expressing tumor cells compared with Nb-BiTE, including U87 cells (EC50 1.5 nM vs. 5.19 nM) and primary CAFs (EC50 0.85 nM vs. 17.48 nM)." (PMID 38031188, 2023). "As for the “physical barrier,” targets that act on the tumor mesenchyme or microvasculature (FAP, CSPG4, etc.)may also improve the penetration of CAR-T cells in the TME." (PMID 38187386, 2023). "Extending this work, the group later described that the MDSC-recruiting and protumorigenic features of FAP/STAT3/CCL2 signaling were conserved in iCCA, reiterating the importance of CAFs and FAP signaling in generating an immunosuppressive stroma that is permissive for tumor progression." (PMID 36708970, 2023). "In addition, there were two other phenotypes namely A-SMA+/Thy-1+(closer to tumor cells in classic ILC) and FAP+/S-100+ (closer to tumor cells in pleomorphic ILC), which showed a trend of significance." (PMID 38192631, 2023). "Elevated levels of IL-6, which is secreted by activated CAFs, particularly FAP + CAFs, contribute to the proliferation of immunosuppressive cells, impairment of anti-tumor cell functions, and ultimately, tumor progression and therapy resistance through various downstream signaling pathways." (PMID 37723510, 2023). "Of note, FAP-targeted vaccines have shown their antitumor function in both in vitro and in vivo experiments, modulating the immunosuppressive microenvironment and decreasing tumor growth and angiogenesis." (PMID 37784082, 2023). "Moreover, fibroblastic expression of FAP has been shown to interfere with cell cycle progression, leading to an increase in tumor cell proliferation." (PMID 38313431, 2023). "We hypothesize that high FAP expression in cancer patients and subsequently uptake of tracer in FAP-directed PET imaging might serve as a whole-body readout for tumor-associated angiogenesis." (PMID 36672341, 2023). "Changes in tumor RNA expression were maintained by day 13 pi with 177Lu-FAP-2287 monotherapy so that 16 of the 43 (84%) RNA transcripts originally identified at day 8 pi still remained significantly differentially expressed, including 13 genes involved in the interferon signaling pathway." (PMID 37086273, 2023). "Moreover, the 68 Ga-FAPI-46 PET biodistribution was strongly similar to the FAP expression pattern detected by IHC in tumor tissues." (PMID 35951090, 2023). "Moreover, due to the high tumor uptake of FAP tracers and low expression of FAP in healthy tissues, FAP is deemed as a promising target for FAP TRT." (PMID 36813980, 2023). "A high expression level of FAP in tumor stroma was reported previously." (PMID 37024301, 2023). "However, prodrug BF211-03, a substrate for FAP, has shown good anti-tumor properties and low normal tissue toxicity." (PMID 37316886, 2023). "FAP expression levels correlate with tumor grade in glial tumors." (PMID 37370912, 2023). "With this study on FFPE tissue samples, we could show that FAP is expressed in tumor cells in the majority of STSs of dogs, cats, and humans." (PMID 37727209, 2023). "Indeed, co-culturing tumor cells with FAP-expressing fibroblasts significantly increased the fraction of tumor cells in the S/G2/M phases." (PMID 38313431, 2023). "However, the combination of FAP-CAR T cells followed by anti-PD-1 synergistically reduced tumor growth and prolonged survival compared with other treatment combinations." (PMID 37607999, 2023). "Notably, forced overexpression of FAP promotes NK cell invasion through matrix in both transwell and tumor spheroid assays, ultimately increasing tumor cell lysis." (PMID 38196606, 2023). "Instead, FAP-positive tumors were characterized by high amounts of tumor vessels." (PMID 36672341, 2023).
tumor (continued). "A fibroblast activation protein (FAP) inhibitor labeled with gallium 68 (68Ga) (FAPI) PET is based on FAP’s molecular targeting, which is known to be highly expressed in cancer-associated fibroblasts, the main cell type in the tumor stroma." (PMID 38202160, 2023). "Importantly, mice vaccinated with FAP and given cyclophosphamide chemotherapy showed significant tumor growth suppression (inhibition ratio: 80%) and longer survival times." (PMID 37496657, 2023). "This emphasizes the involvement of FAP in crucial processes of tumor development." (PMID 37614665, 2023). "Nevertheless, unlike the tumor center, FAP expression in the tumor margin was associated with a higher tumor stage." (PMID 37316886, 2023). "[177Lu]Lu-FAP-2286 showed tolerable side effects and prolonged tumor retention (up to 10 days)." (PMID 36813980, 2023). "FAP is a representative marker of activated CAFs and elevated expression of FAP promotes tumor progression by regulating multiple biological processes related to tumor cell growth, invasion, metastasis, drug resistance and stemness, and is associated with a worse prognosis across most cancer types." (PMID 35951090, 2023). "Despite promising utilities, there are some pitfalls in FAP-targeted tracers, as non-tumor related uptake of [68Ga]Ga-FAPI-04 and [68Ga]Ga-FAPI-46 by degenerative lesions associated with joints and vertebral bones, muscles, scars, head-and-neck, and mammary glands has been reported." (PMID 36986548, 2023). "Besides its connection with angiogenesis and tumor micro-vessel density, FAP has a role in regulating inflammation in the tumor milieu." (PMID 37892020, 2023). "Additionally, the combination of EGFR- and FAP-targeted NIR-PIT achieves suppression of tumor growth in vivo." (PMID 37686288, 2023). "First, we investigated the role of FAP in fibroblasts on tumor cells in vitro." (PMID 37325617, 2023). "Additionally, the investigation encompassed the correlation between postoperative tumor burden, as assessed through volumetric analysis, and the relative FAP level of serum autoantibodies." (PMID 37864148, 2023). "To test the hypothesis, we will characterize the immunohistochemical expression of FAP in tumor samples using a previously validated IHC assay and compare it against tumor uptake of [68Ga]FAPI-46 on PET." (PMID 38011131, 2023). "Except for being tumor-promoting, FAP was also observed to have some tumor-inhibiting properties." (PMID 37784082, 2023). "Among these biomarkers, FAP, a type II transmembrane glycoprotein, whose expression was selectively observed in CAFs and pericytes in most human epithelial cancers, was thought to facilitate tumor growth and proliferation." (PMID 37784082, 2023). "On day 10 pi, tumors in the vehicle control animals reached an MTV of 750 mm3, while significant tumor growth inhibition (TGI) was observed in 177Lu-FAP-2287, anti-PD-1 and the combination group with MTV of 266, 373 and 145 mm3, corresponding to a TGI of 74, 57, and 92%, respectively (P < 0.05)." (PMID 37086273, 2023). "For example, the FAP gene–targeting tumor-derived exosomes-like nanovesicles (eNVs-FAP) could trigger potent and specific cytotoxic T lymphocyte (CTL) immune responses against tumor cells and FAP+ CAFs and remodel immunosuppressive TME in multiple models." (PMID 36922504, 2023). "Thus, FAP(hF1) UCAR T-cell treatment should create a long-lasting CAF-depleted tumor milieu, allowing a window for reconstitution of the endogenous immune system and subsequent TIL activity in this CAF-depleted state." (PMID 37251405, 2023). "FAP(hF1) UCAR T-cells alone significantly reduced tumor growth relative to UT-cell controls." (PMID 37251405, 2023). "Furthermore, ELJNV nanovesicles also reduced the expression of α-SMA, FAP, fibronectin, and collagen I in tumor tissues." (PMID 37328484, 2023). "Furthermore, due to their the immune-evasive property, FAP(hF1) UCAR T cells can be readily combined with autologous tumor-targeting CAR T-cell therapies as well." (PMID 37251405, 2023).